INS (insulin)
Diseases named in the same sentence as INS in open-access papers (continued):
Sharing a sentence is not in itself a finding about the gene and the disease.
hypokalemic periodic paralysis (1 paper, 2013). Hypokalemic periodic paralysis (hypoPP) is characterized by episodes of muscle paralysis lasting from a few to 24-48 hours and associated with a fall in blood potassium levels. "In the K-depleted rat, not a genetic animal model of hypokalemic periodic paralysis, BFT is effective in preventing the paralysis and weakness induced by insulin." (PMID 23874973, 2013).
hypospadias (1 paper, 2025). Hypospadias is the displacement of the urethral meatus on the ventrum of the penis. "Therefore, miR-210 can promote the development of hypospadias through insulin/IGF1 and hypoxia signaling." (PMID 39624466, 2025). "Notably, miR-494, miR-200c, miR-145, miR-6756-5p, miR-182 and miR-210 could promote the development of hypospadias through different signaling pathways, such as TGF-β, MAPK, PI3K/AKT, BMP, insulin/IGF and hypoxia." (PMID 39624466, 2025).
idiopathic cardiomyopathy (1 paper, 2020). A disease of the heart muscle or myocardium proper whose cause is unknown. "Among the antidiabetic medications, insulin use substantially increased the risk of idiopathic cardiomyopathy (HR: 1.59, 95% CI 1.43–1.78)." (PMID 33054769, 2020). "In our study, insulin increased the risk of idiopathic cardiomyopathy." (PMID 33054769, 2020). "Thus, the causal relationship between insulin therapy and the risk of idiopathic cardiomyopathy should be interpreted with caution." (PMID 33054769, 2020).
idiopathic dilated cardiomyopathy (1 paper, 2021). Decreased function of the heart associated with cardiac enlargement and congestive heart failure, of unknown cause. "Trimetazidine applied in idiopathic dilated cardiomyopathy patients, of which trimetazidine improved whole body insulin sensitivity and glucose control in these insulin resistant patients." (PMID 34603021, 2021).
interstitial lung disease (1 paper, 2024). A diverse group of lung diseases that affect the lung parenchyma. "Data on the associations between insulin, pioglitazone, and PTB or interstitial lung diseases are limited." (PMID 39091286, 2024).
intestinal obstruction (1 paper, 2025). Blockage of the normal flow of the intestinal contents within the bowel. "We found that GLP-1RAs were associated with a reduced risk of intestinal obstruction compared to insulin." (PMID 40471297, 2025). "Patients prescribed GLP-1RAs displayed a significantly reduced hazard ratio for the diagnosis of intestinal obstruction compared with patients prescribed insulin at 1, 3, and 5 years." (PMID 40471297, 2025). "Additionally, both studies compared GLP-1RAs with SGLT-2 inhibitors, but the risk of intestinal obstruction associated with GLP-1RAs compared to other commonly used anti-diabetic medications, including insulin and metformin, remains unknown." (PMID 40471297, 2025). "Sulfonylureas, which lower blood glucose by stimulating insulin secretion, and thiazolidinediones, which act as insulin sensitizers by binding to PPAR-γ receptors, are similarly not commonly associated with intestinal obstruction." (PMID 40471297, 2025).
juvenile DM (1 paper, 2022). "There are several types of DM, including type I (insulin-dependent, juvenile DM), type II (non-insulin-dependent, adult-onset DM), and gestational DM." (PMID 35207562, 2022).
keloid (1 paper, 2022). An irregularly shaped, elevated mark on the skin caused by deposits of excessive amounts of collagen during wound healing. "The insulin signalling pathway was activated in keloid lesions with highly upregulated insulin-like growth factor 1 receptor (IGF1R)." (PMID 35709140, 2022).
lagophthalmos (1 paper, 2025). "In this retrospective case–control study, topical application of insulin drops (1 U/mL) was associated with a significantly higher likelihood of complete corneal epithelialization in patients with facial nerve palsy and lagophthalmos compared to artificial tears with a lipid component." (PMID 41303828, 2025). "Despite the growing interest in the use of topical insulin in ophthalmology, available clinical evidence remains limited, especially in patients with facial nerve palsy and lagophthalmos, a group in which standard therapies are often insufficient." (PMID 41303828, 2025).
laryngeal carcinoma (1 paper, 2013). Carcinoma that arises from the laryngeal epithelium. "Based on these data, the Hellenic Cooperative Oncology Group (HeCOG) proceeded with evaluating the prognostic value of the VEGF, EGFR and insulin signaling pathways in laryngeal cancer." (PMID 23950933, 2013).
latent infection (1 paper, 2022). "This could be because the latent infection causes the release of nitric oxide, which improves insulin sensitivity." (PMID 36268223, 2022).
Lewis lung carcinoma (1 paper, 2022). "TRF attenuated the HFD-enhanced spontaneous metastasis of Lewis lung carcinoma (LLC) in mice probably by preventing HFD-induced increases in plasma concentrations of glucose, insulin, proinflammatory cytokines, and angiogenic factors." (PMID 36576605, 2022).
lipomatosis (1 paper, 2021). A neoplastic process characterized by diffuse overgrowth of mature adipose tissue. "Weight, BMI, blood pressure, gamma-GT, leptin, fasting insulin and C-peptide levels, fat mass percentage, and intra/total abdominal fat ratio were significantly higher in each lipomatosis group compared with the lean group." (PMID 34187516, 2021).
lower respiratory tract infection (1 paper, 2024). "The patient was diagnosed with pulmonary thromboembolism with diabetic ketoacidosis with lower respiratory tract infection and treatment was started with recombinant tissue plasminogen activator, hydration, insulin, and IV antibiotics." (PMID 39130871, 2024).
Lumbar scoliosis (1 paper, 2014). "On the basis of these data, it seems prudent to warn insulin-dependent diabetic patients of the potential increased risk of postoperative complications associated with degenerative lumbar scoliosis surgery." (PMID 24606963, 2014).
Lymphatic Metastasis (1 paper, 2021). Transfer of a neoplasm from its primary site to lymph nodes or to distant parts of the body by way of the lymphatic system. "In addition, 112 (35.9%) patients were lymphatic metastasis-positive in the metformin group, while 43 (54.4%) in the insulin group." (PMID 33976288, 2021).
Macrocephaly (1 paper, 2022). Occipitofrontal (head) circumference greater than 97th centile compared to appropriate, age matched, sex-matched normal standards. "We found earlier gestational age (Z = −3.427, P = 0.001), lower neonatal weight (Z = −2.200, P = 0.028), lower incidence of macrocephaly (χ2 = 4.092, P = 0.043) and lower incidence of maternal referral to ICU treatment (P = 0.014) in the insulin treatment group than in the control group." (PMID 36405614, 2022).
malabsorption syndrome (1 paper, 2026). A syndrome resulting from the inadequate absorption of nutrients in the small intestine. "Anorexia, malabsorption syndromes, ectopic ACTH, drugs (thiazide diuretics, insulin, granulocyte growth factor, glucocorticoids), antineoplastic drugs (cisplatin, ifosfamide, anti-EGFR agents, mTOR inhibitors, eribulin, abiraterone)." (PMID 41601884, 2026).
male fertility (1 paper, 2022). A fertility quality of inhering in a male by virtue of the bearer's disposition to initiate, sustain, or support reproduction. "In contrast, PEE/CWE may improve male fertility via effects on circulating glucose and insulin levels." (PMID 35883763, 2022).
malocclusion (1 paper, 2021). "Stimulation by mastication alone triggers insulin secretion and patients with malocclusion tend to show increased insulin resistance." (PMID 33776655, 2021).
Meniere disease (1 paper, 2010). A disease of the inner ear (labyrinth) that is characterized by fluctuating sensorineural hearing loss; tinnitus; episodic vertigo; and aural fullness. "On the contrary, the only adverse event that was considered serious (a case of Meniere's disease) occurred in the insulin GLA group." (PMID 20415692, 2010).
meningococcal disease (1 paper, 2011). "• In children with meningococcal disease, normalization of blood glucose levels occurs within 48 hours, typically with normal glucose intake and without insulin treatment." (PMID 21276273, 2011).
menopausal disorders (1 paper, 2023). "Myo-inositol could be a valid insulin-sensitizing molecule for managing menopausal disorders." (PMID 37461069, 2023).
MODY type 4 (1 paper, 2010). "Deficiencies in pdx1 (MODY type 4) and hnf1bMODY type 5 might be expected to have the most severe effect on insulin production due to the direct feedback by insulin on gene expression or protein activity." (PMID 20587063, 2010).
mucinous neoplasm (1 paper, 2025). "In terms of metabolic parameters, fasting glucose and insulin levels were higher in mucinous neoplasm patients compared to serous cystadenoma group." (PMID 41451009, 2025).
multiple symmetrical lipomatosis (1 paper, 2020). "Of note, human syndromes such as multiple symmetrical lipomatosis (Madelung’s disease), caused by mutations in MFN2, appear chiefly to lower insulin sensitivity." (PMID 32894309, 2020).
muscle disorders (1 paper, 2022). "Glucose metabolism and insulin sensitivity are essential for muscle contraction, and previous evidence has shown that muscle disorders could cause abnormal lipid deposition." (PMID 35137485, 2022).
myoblastomas (1 paper, 1971). "Granular myoblastomas of the cervico-vaginal tract occur in intacts only and particularly in diabetics and those medicated with growth hormone or insulin." (PMID 4335634, 1971).
myoma (1 paper, 2015). "For example, insulin and pioglitazone have been shown to have myoma inhibitory effects and IGF-1 levels decrease in treated diabetics." (PMID 25969688, 2015).
Neurodevelopmental delay (1 paper, 2020). "Recently, several reports have demonstrated that children born to mothers with HG were small for gestational age and had low birth weight, reduced insulin sensitivity, and neurodevelopmental delays during childhood." (PMID 32503221, 2020). "Moreover, HG may result in reduced insulin sensitivity and neurodevelopmental delays at school age in offspring of mothers who experienced HG during pregnancy." (PMID 32503221, 2020).
neuromyelitis optica spectrum disorder (1 paper, 2021). "Neuromyelitis optica spectrum disorder (NMOSD) is associated with inflammatory mediators that may also trigger downstream signaling pathways leading to reduce insulin sensitivity." (PMID 33879088, 2021).
nodular goiter (1 paper, 2017). Goiter characterized by discrete tissue mass(es) that may or may not produce thyroid hormones. "Recent studies suggest an important role of insulin resistance in the formation of nodular goiter." (PMID 29214182, 2017).
oral candidiasis (1 paper, 2020). Infection of the mucosal lining of the mouth with the fungus Candida albicans. "Oral candidiasis is not uncommon due to the combination of atrophic tongue changes and insulin resistance, and careful mouth hygiene is required to prevent painful fissuring." (PMID 32276665, 2020).
ovarian adenocarcinoma (1 paper, 2021). An adenocarcinoma that arises from the ovary. "The human ovarian adenocarcinoma cell line OVCAR-3 was cultivated in RPMI 1640 medium with 0.01 mg/mL bovine insulin and 20% FBS." (PMID 33833336, 2021).
ovary atrophy (1 paper, 2020). Shrinking or reduction in function of the ovaries, often related to aging or hormonal changes. "Our data clearly indicate that upon chronic enteric dysbiosis, a specific NF-κB-dependent reduction of insulin/PI3K signaling in MTs is the trigger of fluid accumulation and fat body wasting but not ovary atrophy." (PMID 32839462, 2020).
panniculitis (1 paper, 2024). Inflammation of the subcutaneous adipose tissue. "Histopathologic analysis revealed the patient had a panniculitis reaction to exogenous insulin, which was proposed to result from insulin auto-antibodies forming IgG complexes with exogenous insulin, leading to a type III hypersensitivity reaction." (PMID 39622650, 2024).
papillary thyroid cancer (1 paper, 2022). "Although rs1042044 had nothing to do with insulin secretion, it was reported to be associated with susceptibility of T2DM in a Chinese literature and the risk of papillary thyroid cancer among the Egyptian population in a recent study." (PMID 36528605, 2022).
pathological myopia (1 paper, 2021). Excessive axial myopia associated with complications (especially posterior staphyloma and CHOROIDAL NEOVASCULARIZATION) that can lead to BLINDNESS. "Insulin positively correlates with the length of the eye axis and is increased in the vitreous and serum of patients with pathological myopia (PM)." (PMID 34001063, 2021).
POMC deficiency (1 paper, 2018). "In order to address if glucose tolerance impairment triggered by POMC deficiency is caused by decreased insulin sensitivity, another cohort of arcPomc−/−:Cre and Cre female mice were subjected to an ITT." (PMID 30283405, 2018). "Regardless the pathway involved, since pyruvate tolerance was unaltered in our model of POMC deficiency, impaired glucose uptake rather than liver glucose production might be responsible for insulin intolerance." (PMID 30283405, 2018).
Pompe disease (1 paper, 2017). "The information regarding mTOR signaling in Pompe muscle cells is limited to a recent finding of reduced insulin‐stimulated mTORC1 activation in two cellular models of Pompe disease—GAA‐knockdown C2C12 myoblasts and GAA‐deficient human fibroblasts from infantile Pompe patients." (PMID 28130275, 2017).
Postpericardiotomy Syndrome (1 paper, 2021). A nonspecific hypersensitivity reaction caused by TRAUMA to the PERICARDIUM, often following PERICARDIOTOMY. "We revealed a lower rate of postpericardiotomy syndrome (PCTS) in patients on insulin pump therapy compared to patients prescribed bolus insulin therapy in the early postoperative period (p = 0.03)." (PMID 34362176, 2021).
postural orthostatic tachycardia syndrome (1 paper, 2026). A condition characterized by development of symptoms while standing. "Postural orthostatic tachycardia syndrome (POTS) is associated with multiple autonomic symptoms, including gastrointestinal (GI) complaints, and has been linked to insulin resistance." (PMID 42156945, 2026).
prolactinoma (1 paper, 2022). "Out of the diabetic prolactinoma patients two patients were treated with metformin and one with metformin and insulin." (PMID 36558529, 2022).
protein metabolism (1 paper, 2023). "It is a chronic carbohydrate, fat, and protein metabolism disorder characterized by high blood glucose levels resulting from the absence of insulin or insulin resistance." (PMID 37398913, 2023).
Proteinuria (1 paper, 2014). Increased levels of protein in the urine. "Proteinuria was positively associated in insulin-dependent patients but not in the group that were not using insulin." (PMID 24955234, 2014).
protozoal infections (1 paper, 2022). "The direct association between protozoal infections and blood insulin levels appears to have no precedent in prior literature." (PMID 36096405, 2022).
pseudohypoparathyroidism (1 paper, 2007). "Alternative first exons for GNAS transcripts lead to distinct products, which in human have been linked to osteodystrophy and pseudohypoparathyroidism phenotypes, while in mouse GNAS heterozygous mutants show metabolic abnormalities and insulin hypersensitivity (see Glycolysis above)." (PMID 17244347, 2007).
Pseudomonas infection (1 paper, 2022). Infections with bacteria of the genus pseudomonas. "Moreover, the beneficial effect of Xuebijing against Pseudomonas infection depended on insulin, p38 MAPK, Wnt, DBL-1/TGF-β, ELT-2, and programmed cell death (PCD)-related signals." (PMID 36120363, 2022). "In C. elegans, p38 MAPK, insulin, Wnt, DBL-1/TGF-β, ELT-2, and PCD-related signals were required for beneficial effects of Xuebijing against Pseudomonas infection and intestinal colony accumulation." (PMID 36120363, 2022).
Psoas abscess (1 paper, 2021). Abscess of the PSOAS MUSCLES resulting usually from disease of the lumbar vertebrae, with the pus descending into the muscle sheath. "This case highlights the risk of the use of unsterile subcutaneous insulin injections leading to psoas abscess, which can be complicated by a spinal epidural abscess." (PMID 34790470, 2021).
ptosis (1 paper, 2022). The drooping of the upper eyelid. "Significant improvement was seen in terms of his discomfort; however, ptosis and ocular mobility improved only moderately after treatment with intravenous methylprednisolone, and the patient was discharged on a new insulin regimen." (PMID 35884709, 2022).
puberty (1 paper, 2020). The process of sexual maturation mediated by the neuroendocrine system in mammals. "Puberty is characterized by marked elevation in sex steroids, which are associated with a clear reduction in insulin sensitivity in both boys and girls." (PMID 33013688, 2020).
puerperal infection (1 paper, 2024). An infection occurring in puerperium, the period of 6-8 weeks after giving birth. "In conclusion, the present study showed that HbA1c (at 32 weeks), insulin at 120 min after glucose loading, and HOMA-IR levels can effectively predict PROM in GDM patients and are associated with postpartum adverse pregnancy outcomes, such as puerperal infection and postpartum hemorrhage." (PMID 39216124, 2024).
pyometra (1 paper, 2024). "Notwithstanding, molecular mechanisms involved in the insulin-resistant state of bitches in diestrus or with pyometra have been explored in the past years, bringing new insights about insulin resistance in dogs." (PMID 38539988, 2024). "The septic and inflammatory characteristics of pyometra additionally decrease insulin sensitivity during diestrus." (PMID 38539988, 2024). "These pyometra epidemiological characteristics were associated with a significantly higher age and higher size of bitches in the studies that have compared insulin sensitivity among bitches with pyometra and other estrus cycle phases." (PMID 38539988, 2024). "Pyometra represents an additional insulin resistance factor over diestrus due to its inflammatory and septic nature." (PMID 38539988, 2024). "Pyometra represents additional inflammatory and septic negative influence on insulin sensitivity, and its diagnosis associated with CDM is therapeutically challenging." (PMID 38539988, 2024). "Fructosamine fails to evidence insulin resistance in bitches with pyometra, and showed reduced levels compared with bitches in diestrus, a finding considered to be the result of the lower albumin serum concentration levels observed in the bitches with pyometra." (PMID 38539988, 2024).
relapsing-remitting MS (1 paper, 2020). "Interestingly, lean patients with relapsing-remitting MS showed increased concentrations of small HDL-C and increased lipoprotein insulin resistance index, which may promote the progression of disease in these patients." (PMID 32178676, 2020).
renal tumors (1 paper, 2020). "In this study, the diabetic balance had no influence on the incidence of renal tumors, but insulin seemed to speed up tumor growth." (PMID 32150972, 2020).
Retinal atrophy (1 paper, 2023). A nonspecific term denoting wasting, especially as a result of degeneration, of the retinal pigment epithelium (RPE) and neurosensory retinal cells. "Eventually, insulin and statin therapy proved effective in reversing the vascular lesions, although retinal atrophy finally ensued." (PMID 37800092, 2023).
retinoblastoma (1 paper, 2018). A malignant tumor that originates in the nuclear layer of the retina. "The insulin signalling pathway was found to be enriched in retina and retinoblastoma tissues." (PMID 29914080, 2018). "Thus, the activation of the insulin signalling pathway had different roles in retina and retinoblastoma." (PMID 29914080, 2018). "Important mediators of the insulin pathway such as Akt, BCL-2 antagonist of cell death (BAD), FOXO1, and FASN were found to be phosphorylated in both retina and retinoblastoma tissues." (PMID 29914080, 2018).